MTOR (mechanistic target of rapamycin kinase)
Diseases named in the same sentence as MTOR in open-access papers (continued):
Sharing a sentence is not in itself a finding about the gene and the disease.
colon carcinoma (continued). "High‐throughput screening of an anticancer drug shows MTA1 knockout increases the sensitivity of colon cancer to mitochondrial bioenergetic metabolism‐targeted drugs and mTOR inhibitors." (PMID 37442756, 2023). "To verify the clinical relevance of MTA1 and ATP5A expression in tumors from clinical patients, we analyzed the expression of cytoplasmic MTA1, ATP5A, mTOR, and p‐mTOR in tissues from colon cancer patients." (PMID 37442756, 2023). "The PI3K/Akt/mTOR signaling pathway plays an important role in the occurrence and development of colon cancer." (PMID 36971681, 2023). "We established a colon cancer liver metastasis model and treated the mice with the mTOR inhibitor rapamycin." (PMID 37442756, 2023). "Results from in vitro studies also demonstrate that leptin activates the phosphoinositide 3-kinase (PI3K)/protein kinase B (PKB/AKT)/mammalian target of rapamycin (mTOR) signaling pathway, enhancing the proliferation of human colon cancer cells." (PMID 38003638, 2023). "mTOR signaling suppression reduces aldehyde dehydrogenase activity, which is abundant in immature cells, such as stem cells, in colon cancer." (PMID 36816969, 2023). "Caco-2 cells, intestinal epithelial cells derived from colon carcinoma and responsive to gliadin, were used to study the effects of gliadin on the mTOR and autophagy pathway." (PMID 35409015, 2022). "The mentioned signaling pathway (PI3K/Akt/mTOR) significantly controlled colon cancer stem cell proliferation and survival where stem cells were found to cause metastasis and recurrence." (PMID 35795855, 2022). "ADAMTS9-AS1 can inhibit apoptosis and autophagy through the PI3K/AKT/mTOR signaling pathway and promote bladder cancer progression while inhibiting colon cancer cell progression through the Wnt/β-catenin signaling pathway." (PMID 36092903, 2022). "For example, pharmacological activation of Mechanistic target of rapamycin (mTOR) and their downstream factors wound synergize anti-PD-1 treatment in the colon cancer mouse model." (PMID 35281061, 2022). "It was consistent with previous research in colon cancer and papillary thyroid carcinoma, which showed that apatinib induced cell apoptosis via inactivating Akt/mTOR signalling pathway." (PMID 35315581, 2022). "LLEFE was able to significantly (P < 0.05) upregulate SOD1, CAT, and GSH and significantly (P < 0.05) downregulate PI3K, Akt, and mTOR expression in HT-29 colon cancer cells." (PMID 35586809, 2022). "In a murine model with an engineered block in Stat3 signaling in macrophages, gut microflora led to robust colitis, activation of mammalian target of rapamycin (mTOR), and the development of colon cancer." (PMID 35681791, 2022). "For example, inositol-6 phosphate was shown to induce autophagy by inhibiting the Akt/mTOR pathway, which led to the autophagy-mediated death of HT-29 colon cancer cells." (PMID 36589681, 2022). "mTOR is a protein that regulates the growth and proliferation of cancer cells by sensing nutrition levels and growth factors; it is highly expressed in colon cancers." (PMID 35887090, 2022). "Previous investigations have reported that hyperactivation of mTOR signaling is one of the major factors contributing to the development of colon cancer." (PMID 36428613, 2022). "In this context, we aimed to provide an accumulative account of recent updates on mTOR pathway and its inhibitors with special focus on the microbial infection control, inflammatory bowel disease treatment, and colon cancer treatment." (PMID 36293326, 2022).
colon carcinoma (continued). "As the research found, WSP1 induces autophagy and inhibits EMT by downregulating the PI3K/AKT/mTOR pathway, thereby inhibiting colon cancer migration." (PMID 36544104, 2022). "In vitro, ghrelin is reported to induce colon cancer cell proliferation through the GHS-R/Ras/PI3K/Akt/mTOR axis." (PMID 36241983, 2022). "OA also exhibited anticancer activity in colon cancer by regulating the mTOR and AMPK signaling pathways." (PMID 35887090, 2022). "In a sample of 871 male and 687 female colon cancer patients, it was discovered that genetic diversity linked with the AKT/mTOR pathway contributes to both colon and rectal cancer risk." (PMID 36293326, 2022). "Withaferin A has also demonstrated anticancer activity against colon cancer by targeting and downregulating Notch-1 signaling via targets such as Hey-1 and Hes-1 and concurrently suppressing crosstalk between Notch-1 and Akt/mTOR pathways." (PMID 35335986, 2022). "Piperlongumine, a Piper longum-derived compound, induces antiproliferation and apoptosis of colon cancer cells by suppressing Ras/PI3K/AKT/mTOR." (PMID 36139919, 2022). "qRT-PCR and Western blotting were used to explore the effects of the extracts on the AKT/mTOR pathway and preliminarily explain their mechanism of inhibiting human colon cancer cells." (PMID 35208943, 2022). "The activation of AMPk not only can induce the overexpression of caspase-3, caspase-8, and caspase-9, that would lead to cancer cell autophagy, but also regulates the mTOR, hence inducing autophagy and apoptosis in colon cancer cells." (PMID 35887090, 2022). "This interplay between SLC6A14 and mTOR was also recently confirmed in colon cancer LS174T cell line treated with α-MT." (PMID 35372502, 2022). "The knockdown of SHANK1 inhibited viability and induced apoptosis in colon cancer cell lines through AKT/mTOR signaling pathways." (PMID 35468874, 2022). "The mutant BRAF-driven colon cancer cells depend upon Mcl-1 stabilization to exhibit resistance to the mammalian target of rapamycin (mTOR) inhibitor everolimus." (PMID 36045907, 2022). "It was reported that OA induced autophagy in vitro in SW-480 and HCT-116 colon cancer cell lines in an AMPk-dependent manner, by inhibiting the mTOR signaling pathway and leading to colon cancer apoptosis." (PMID 35887090, 2022). "In colon cancer cells, FBXW7 deficiency results in accumulation of mTOR, thus in turn favoring EMT-related stem-like properties." (PMID 35515121, 2022). "Active VD3 treatment also reduced cell proliferation, altered the mitochondrial membrane potential, inhibited the PI3K/Akt/mTOR pathway, and suppressed glycolysis alongside inducing cell cycle arrest and apoptosis in several human colon cancer cell lines." (PMID 35326689, 2022). "The Akt/mTOR signalling pathway plays an important role in the survival and growth of cancer cells, such as colon cancer cells." (PMID 35208943, 2022). "Through the TSC2 complex, a relationship has been demonstrated between Wnt signaling, which is active in most colon tumours, and mTOR." (PMID 36293326, 2022). "In colon cancer cell lines, EGFR signaling increased lipid droplet density by activation of PI3K/mTOR pathway and loss of Foxo3." (PMID 36360201, 2022). "Ferroptosis-related lncRNAs can predict prognosis as well as reflect other conditions of colon cancer, including hypoxia condition; immune-related factors; somatic variants; and signaling pathways such as MAPK, mTOR, and the glutathione metabolism pathway." (PMID 35884370, 2022). "Isovitexin induces tumor cell apoptosis and inhibits colon cancer cell growth through PI3K/Akt/mTOR signaling pathway." (PMID 35847368, 2022). "MA can significantly inhibit tumor formation in azomethane/dextran sodium sulfate mice and xenotransplantation mice and regulate the AMPK/mTOR pathway, thereby inhibiting the growth of colon tumors." (PMID 36118079, 2022).
colon carcinoma (continued). "W922, a PI3K/AKT/mTOR inhibitor, induces antiproliferation and autophagy of colon cancer cells by down-regulating PI3K/AKT/mTOR." (PMID 36139919, 2022). "SIRT6 can not only upregulate the expression of tumor suppressors phosphatase and tensin (PTEN), and phosphatidylinositol-4,5-biphosphate (PIP2), but also can downregulate AKT1, mTOR, cyclin D1, and c-myc to inhibit the progression of colon cancer." (PMID 35172823, 2022). "Another study showed that Rhus coriaria ethanolic extract induced autophagy and increased the overall level of protein ubiquitination and the degradation of several proteins including mTOR protein in HT-29 colon cancer cells." (PMID 35712465, 2022). "It has been found to induce cell autophagy and apoptosis by inhibiting the PI3K-Akt-mTOR signaling pathway, which has been proven by decreasing the expression of p-PI3K, p-Akt, and p-mTOR in colon cancer cells." (PMID 36428613, 2022). "The anaphase bridge index (ABI) in colon cancer cells was also increased due to forced activation of mTOR via the upstream regulator Akt." (PMID 36428613, 2022). "More importantly, Lar also increased AMPK phosphorylation and suppressed mTOR phosphorylation in colon cancer cells." (PMID 36251949, 2022). "Myricetin induces treatment-related apoptosis and autophagy in colon cancer by inhibiting the PI3K/Akt/mTOR signaling pathway." (PMID 36091790, 2022). "Pleckstrin homology such as domain family A member 2 (PHLDA2) knockdown inhibits proliferation and PI3K, promotes apoptosis and autophagy, and blocks EMT by PI3K/AKT/mTOR signaling in colon cancer cells." (PMID 36139919, 2022). "MM-129 is a novel inhibitor targeting BTK/PI3K/AKT/mTOR and PD-L1, as it possesses antitumor activity against colon cancer." (PMID 34452183, 2021). "The combination of cetuximab with everolimus (mTOR inhibition) showed a tendency for synergistic effects in the same two colon cancer PDX models, where, in particular, two complete regressions were remarkable." (PMID 34885128, 2021). "It inhibits cell cycle progression and proliferation and induces apoptosis and autophagy in human colon cancer cells by inhibiting the PI3K/Akt/mTOR signaling." (PMID 34830339, 2021). "Our analysis revealed that the novel MM131 was able to reduce mTOR concentrations in both colon cancer cell lines after 24 h incubation in comparison with untreated cells and the inhibitory effect was much stronger than the reference compound." (PMID 33918514, 2021). "Activation of AMPK by AICAR treatment in BR colon cancer cells suppressed cell proliferation by inhibiting Akt and mTOR and activating ACC." (PMID 34829834, 2021). "Here, we demonstrate that mTOR inhibitors and auranofin synergize to induce cancer cell death in gastric and colon cancer cells, whilst has little effect on normal NRK-52E and MPM cells, suggesting that this combination is not generally toxic." (PMID 33754064, 2021). "In colon cancer, 3D spheroids display low activities of mTOR, S6K and Akt signaling pathways compared to cells grown in 2D cultures, suggesting distinct signaling rewiring in 3D environment." (PMID 34277708, 2021). "For example, Cryptotanshinone, which is derived from Salvia miltiorrhiza Bunge, suppresses CT26 colon cancer cell angiogenesis via inhibiting the PI3K/Akt/mTOR signaling pathway, nuclear hypoxia inducible factor-1α (HIF-1α), VEGF and VEGFR gene activation." (PMID 34163519, 2021). "A study on nude mice with subcutaneous human HCT-116 colon tumor xenografts treated with everolimus observed the direct inhibition of tumor growth and a dose-dependent decline in phospho-S6 kinase levels, an mTOR target." (PMID 34361836, 2021). "A previous study has also reported that Murraya koenigii leaves extract induced mitochondrial apoptosis in DLD-1 colon cancer cells by downregulating mTOR/AKT pathway." (PMID 33990623, 2021).
colon carcinoma (continued). "In the present study, we found that mTOR inhibitors or auranofin treatment alone induced autophagy in colon cancer cells, while the inductive effect was stronger when used in combination." (PMID 33754064, 2021). "Propionate was reported to activate autophagy in colon cancer cells via decreased mTOR activity and enhanced AMP kinase activity." (PMID 33912026, 2021). "GOLPH3 can promote tumor cell proliferation in colon cancer through PI3K/Akt/mTOR and Wnt/β-catenin signaling, and its overexpression can be considered an important sign to evaluate the prognosis of CRC." (PMID 33680216, 2021). "We first investigated the combined effects of mTOR and TrxR inhibitors on the viability of human gastric and colon cancer cell lines." (PMID 33754064, 2021). "Apigenin induces autophagic cell death in human colon cancer (HCT-116) cells via inhibition of the PI3K/AKT/mTOR signalling pathway." (PMID 34094892, 2021). "In hepatic and colon cancer cells, pharmacological inhibition of mTOR activity by rapamycin decreases OGT expression by regulating protein stability." (PMID 33801653, 2021). "NFκB in SW620 cells suggested that AS inhibited AKT/mTOR signaling cascades, NFκB and β-catenin expression levels thus activating cytoprotective autophagy in human colon cancer cells." (PMID 34031264, 2021). "In xenograft mouse model, our results also showed that DHOK activates the mTOR signaling pathway, decreases autophagy level and inhibits the tumorigenesis of colon cancer." (PMID 34977014, 2021). "Mammalian target of rapamycin (mTOR) is frequently activated and overexpressed in a variety of cancers, including colon cancer." (PMID 33067464, 2020). "MiR-214-3p also participates in the tumorigenesis and stemness of colon cancer through the mTOR/β-catenin pathway." (PMID 32413870, 2020). "The CXCL13/CXCR5 axis promotes tumor progression through the PI3K/AKT/mTOR pathway, contributes to poor prognosis in clear cell renal cell carcinoma, and promotes the growth and invasion of colon cancer cells via the PI3K/AKT pathway." (PMID 33213490, 2020). "Asiatic acid affects migration, invasion, and apoptosis of colon cancer SW480 and HCT116 cells; it regulates Pdcd4 through the PI3K/Akt/mTOR/p70S6K signaling pathway and inhibits migration and invasion and induces apoptosis of the colon cancer cells." (PMID 32104680, 2020). "mTOR primarily resides within the cytoplasm, but nuclear localization has also been documented in rhabdomyosarcomas, human fibroblasts and colon carcinoma cells." (PMID 31338320, 2019). "The previous studies have suggested that hesperidin induces apoptosis and autophagy through inhibition of the PI3K/Akt/GSK-3β/mTOR pathway in colon cancer." (PMID 31815144, 2019). "The dual inhibitor, BEZ235 can inhibit not only the over-expressed PI3K/Akt/mTOR signalling pathway in colon cancer cells but also the PD-L1 expression, the later can then increase the sensitivity of cancer cells to T cell-mediated killing." (PMID 30770752, 2019). "The data showed that adenine activated AMP-activated protein kinase (AMPK) signaling contributing to autophagic cell death through mTOR in both colon cancer cell lines." (PMID 31611925, 2019). "Numerous data show decreased cell proliferation and increased caspase-3 activity after the use of mTOR inhibitors in many cases of tumours such as pancreatic, breast, and colon cancer." (PMID 30848427, 2019). "In this study, we showed that TRPV4 knockdown impaired the activation of AKT in colon cancer cells, consequently leading to inactivation of the mTOR and S6K pathway, and attenuated phosphorylation of 4E-BP1 and S6 ribosomal protein." (PMID 31189890, 2019).
colon carcinoma (continued). "The PI3K/AKT/mTOR pathway is dysregulated in a high number of cancer types such as colon cancer and, thus, its pharmacological inhibition has been considered as an attractive approach for treatment." (PMID 31151160, 2019). "Adenine-inhibited cell proliferation in both colon cancer cell lines was restored with increased levels of mTOR phosphorylation in the presence of AMPK inhibitor dorsomorphin." (PMID 31611925, 2019). "In conclusion, this research presumed that deoxyshikonin inhibited the proliferation and apoptosis of colon cancer via down-regulating PI3K/Akt/mTOR partway." (PMID 31230505, 2019). "Studies using 31P-NMR spectroscopy have demonstrated that inhibition of PI3K/AKT/mTOR signalling pathway by PI-103 reduced choline kinase activity, resulting in decreased in PCho in colon cancer cells." (PMID 30056610, 2019). "In our study, we demonstrated that adenine significantly induced AMPK activation and inhibited the phosphorylation of downstream mTOR in both colon cancer cell lines." (PMID 31611925, 2019). "Nilotinib (PDGFR tyrosine kinase inhibitor) combined with everolimus (mTOR inhibitor) decreases cell growth and increases apoptosis of colon cancer." (PMID 30803211, 2019). "The stimulation of the mTOR pathway followed by translational deregulation and accelerated G1-S transition was implicated in inducing genomic instability and Apc LOH in a colon cancer mouse model." (PMID 31799437, 2019). "We evaluated the impact of the allosteric (rapamycin) and two catalytic mTOR inhibitors (AZD8055, AZD2014) on the survival of four colon cancer cell lines, characterized by specific mutations, leading to activated Ras/MAPK and PI3K signaling pathways." (PMID 31627299, 2019). "Activated AKT/mTOR signaling pathway has been reported in many types of human cancers such as liver and colon cancers." (PMID 31027244, 2019). "The study has shown that, polyether mimicking acetogenin (AA005) decrease the phosphorylation of mTOR through suppression of ATP production in colon cancer cells lines." (PMID 31481122, 2019). "For example, in colon cancer HC4T, we found 12 of 79 variants were specific to FFEP DNA in addition to 67 common variants including three key mutations (in BRAF, MTOR and RUNX1)." (PMID 30680068, 2018). "For instance, CXCL6 secretion is increased by fibroblast-derived CXCL12/SDF-1α, which also enhances colonic cancer metastatic potential through the PI3K/Akt/mTOR pathway." (PMID 30237403, 2018). "Previous reports support PI3K/Akt/mTOR pathway is critical for the maintenance of colon cancer stem cells." (PMID 29970892, 2018). "eIF and mTOR expression were analysed on protein and mRNA level in primary low and high grade colon carcinoma (CC) and rectum carcinoma (RC) samples in comparison to non-neoplastic tissue without any disease-related pathology." (PMID 29254159, 2017). "Our findings demonstrate that R. coriaria inhibits the viability and colony growth of colon cancer cells through inactivation of proteasome-dependent degradation of mTOR." (PMID 28912474, 2017). "AKT, a serine/threonine protein kinase and mammalian target of rapamycin (mTOR) plays a critical role in the proliferation and resistance to apoptosis that are essential to the development and progression of colon cancer." (PMID 28972559, 2017). "In this study, for the first time, we investigated the influence of InsP6 on the activity of mTOR by means of p70S6K1 activity analysis in human colon cancer cells." (PMID 28972559, 2017). "Another study reported that total saponins of A. membranaceus (AST) possess potential antitumorigenic effects in human colon cancer cells and tumor xenografts through modulation of both mTOR and ERK signaling pathways." (PMID 29225515, 2017). "Our results demonstrate that R. coriaria exerts its anti-colon cancer effect at least partly through inactivation of mTOR, concomitant with stimulation of the global protein ubiquitination and the ubiquitin proteasome system." (PMID 28912474, 2017).